TRAV9-2 (T cell receptor alpha variable 9-2)
Description:
V region of the variable domain of T cell receptor (TR) alpha chain that participates in the antigen recognition. Alpha-beta T cell receptors are antigen specific receptors which are essential to the immune response and are present on the cell surface of T lymphocytes. Recognize peptide-major histocompatibility (MH) (pMH) complexes that are displayed by antigen presenting cells (APC), a prerequisite for efficient T cell adaptive immunity against pathogens. Binding of alpha-beta TR to pMH complex initiates TR-CD3 clustering on the cell surface and intracellular activation of LCK that phosphorylates the ITAM motifs of CD3G, CD3D, CD3E and CD247 enabling the recruitment of ZAP70. In turn ZAP70 phosphorylates LAT, which recruits numerous signaling molecules to form the LAT signalosome. The LAT signalosome propagates signal branching to three major signaling pathways, the calcium, the mitogen-activated protein kinase (MAPK) kinase and the nuclear factor NF-kappa-B (NF-kB) pathways, leading to the mobilization of transcription factors that are critical for gene expression and essential for T cell growth and differentiation. The T cell repertoire is generated in the thymus, by V-(D)-J rearrangement. This repertoire is then shaped by intrathymic selection events to generate a peripheral T cell pool of self-MH restricted, non-autoaggressive T cells. Post-thymic interaction of alpha-beta TR with the pMH complexes shapes TR structural and functional avidity.
Synonyms: TCRAV22S1; TCRAV9S2; TRAV92
Gene: T-cell receptor variable (V) gene on chromosome 14 (21,941,128 to 21,941,657, forward strand). Ensembl gene ENSG00000211793.
Subcellular location: Cell membrane
Gene Ontology:
Biological process: adaptive immune response
Cellular component: immunoglobulin complex; plasma membrane
Homologues: Orthologues: macaque TRAV9-2 (76% identical), rat Trav6-1 (74% identical), rat AABR07017745.3 (73% identical), rat LOC100362949 (73% identical), mouse Trav6-2 (71% identical), mouse Trav6-6 (71% identical), mouse Trav6d-6 (71% identical), mouse Trav6n-6 (71% identical), mouse Trav6-1 (71% identical), mouse Trav6d-3 (70% identical), mouse Trav6d-4 (70% identical), mouse Trav6-3 (69% identical), and 5 more. Paralogues in human: TRAV9-1 (70% identical), TRAV18 (52% identical), TRAV40 (49% identical), IGKV1OR2-108 (33% identical), IGKV1-12 (32% identical), IGKV1-27 (32% identical), IGKV1-39 (32% identical), IGKV1-9 (32% identical), IGKV1D-12 (32% identical), IGKV1D-39 (32% identical), IGKV1-33 (31% identical), IGKV1-5 (31% identical), and 81 more.
Diseases named in the same sentence as TRAV9-2 in open-access papers:
TRAV9-2 is named in the same sentence as 1 disease in open-access papers, as found by Europe PMC text mining. Sharing a sentence is not in itself a finding about the gene and the disease.
TRAV9-2 shares sentences with these, for which no sentence is quoted: COVID-19 (1 paper).